INS (insulin)
Diseases named in the same sentence as INS in open-access papers (continued):
Sharing a sentence is not in itself a finding about the gene and the disease.
diabetes (continued). "Although it has been established that diabetes increases susceptibility to infections, the role of insulin (INS) in the immune response is unknown." (PMID 27226621, 2016). "Secondly, increased concentration of the pro-inflammatory cytokines such as TNF-α and IL-6 associated with obesity and diabetes might impair insulin action by suppressing insulin signal transduction." (PMID 27581604, 2016). "The results of the study suggested that exposure to POPs among children might affect insulin secretory function, which could lead to an increased risk of developing diabetes." (PMID 27266903, 2016). "Diabetes is a chronic disease that is characterized by hyperglycemia, either resulting from a deficiency of insulin secretion, e.g., by autoimmunogenic destruction of the insulin producing pancreatic cells, or by an impaired insulin action." (PMID 26848666, 2016). "Experimental evidence suggests that, for diabetic patients, a subclinical chromium deficiency is linked to elevated blood glucose, insulin, and lipid levels that may interfere with the management of diabetes." (PMID 27687012, 2016). "In addition, as is widely known, it is thought that one of the major cause of Japanese diabetes is a deficiency of insulin secretion." (PMID 27843494, 2016). "For example, GHRH antagonism may improve some of the lipid, renal, and vascular complications of low insulin-associated diabetes." (PMID 27777568, 2016). "Further studies are needed to verify the functional interaction between WFS1 and TRPM5 in the regulation of insulin secretion and how this downregulation may contribute to diabetes‐like phenotype of WFS1‐deficient mice." (PMID 27053292, 2016). "In future studies, it may be important to assess the individual effect of these influences, such as measures of aldosterone, directly on measures of glucose, insulin, and diabetes risk, to help determine if and how FEK can be used in future studies." (PMID 27280455, 2016). "In addition, three studies reported a beneficial association between mid-life PA and diabetes preconditions, two reported metabolic syndrome and one reported insulin sensitivity." (PMID 26845035, 2016). "Development of partially insulin-deficient Diabetes in rats induced significant alterations in the microarchitecture of long bones (decreases in femoral metaphysis trabecular bone area, osteocyte density, and osteoclast TRAP activity and an increase in bone marrow adiposity)." (PMID 27840829, 2016). "In conclusion, our overall data suggests that insulin levels are significantly lower in Japanese subjects than Caucasian subjects and that insulin deficiency may play a major role in causing excess diabetes in Japanese men." (PMID 27830830, 2016). "High levels of angiotensin II have been reported to possibly play a key role in glucose and insulin regulation and may increase the risk of diabetes." (PMID 28066203, 2016). "When considering insulin as one of the most plausible biological mechanisms underlying the link between obesity and diabetes and a significantly increased risk of BC mortality, it is remarkable that a lowering of insulin by 25% is associated with a 5% absolute improvement in BC mortality." (PMID 27356748, 2016). "Decreasing insulin secretion in childhood might be responsible for the risk of developing diabetes later in life." (PMID 27266903, 2016). "Therefore, in addition to controlling blood sugar levels, controlling insulin levels is essential for patients with type 2 diabetes mellitus, because of this link with atherosclerosis-associated diseases." (PMID 27832775, 2016). "The observed excess risk of cancer in persons with diabetes may, to some extent, be a consequence of anti-diabetic drug therapies, such as exogenous insulin." (PMID 26924393, 2016). "Thus, the aim of this study was to explore the effects of a wide range of KCNJ11 mutations, and of diabetes duration, in a large sample (n = 127) of patients who attempted to transfer to sulfonylureas from insulin." (PMID 27033559, 2016).
diabetes (continued). "Diabetes mellitus is a metabolic disorder characterized by loss of glucose homeostasis occurring due to defects in insulin secretion or insulin action resulting from impaired metabolism of glucose, lipids and other energy yielding fuels such as lipids and proteins." (PMID 27538464, 2016). "However, defective insulin signalling has also been identified in the central nervous system in diabetes, and has been linked to altered nutrient homeostasis, an increased risk of Alzheimer’s disease and changes in lifespan." (PMID 27514532, 2016). "Diabetes represents a group of human diseases characterized by prolonged, elevated levels of blood glucose resulting from insulin deficiency or impaired responsiveness of insulin-target cells to circulating insulin." (PMID 27840833, 2016). "Diabetes mellitus (DM) is a metabolic disorder in the endocrine system due to either an absolute deficiency in insulin secretion or reduction in the biological effectiveness of insulin." (PMID 26508987, 2015). "In the present study, an in-depth analysis on the association among the family history risk categories of diabetes and insulin secretion, insulin resistance, and prevalence of diabetes was carried out using data from the 2007–2008 DMS survey of Chinese adults aged 20 years or older." (PMID 25664814, 2015). "Systemic diseases such as chronic kidney disease, chronic respiratory disease, diabetes mellitus, and malignancies are more prevalent in the older adults, and may cause weight loss, which in theory would be associated with improved insulin sensitivity." (PMID 26074813, 2015). "The data presented here identify a novel regulatory mechanism linking fasting and insulin to signal transduction in the brain, which may help to elucidate the molecular basis of the association between diabetes and brain decline in neurodegenerative diseases." (PMID 26499801, 2015). "Diabetes induction by islet-reactive Teff cells severely inhibited chemokine production by β-islet cells; however, their active insulin-secreting status suggests that the loss of chemokine expression by the islet cells is not merely a consequence of their destruction by Teff cells alone." (PMID 25946021, 2015). "Interestingly, polymorphisms in the LPIN1 and LPIN2 genes are associated with traits of metabolic disease, including insulin sensitivity, diabetes and increased blood pressure, as well as the response to thiazolidinediones." (PMID 26232096, 2015). "The most common causes of DKA may change as the child matures or if their diabetes management changes, for example switching from insulin by injection to insulin pump therapy." (PMID 26323283, 2015). "Importantly, lower insulin sensitivity is associated with increased risk of developing type 2 diabetes mellitus, hypertension, coronary heart disease, stroke, and cancer in the long-term." (PMID 26061526, 2015). "For diabetes risk markers (insulin and HOMA) time spent in SB and LIPA had the opposite relationship, suggesting that replacing sitting time with light activity might be beneficial." (PMID 26461112, 2015). "Insulin may be a marker of more severe and/or longer duration of diabetes and, therefore, risk of micro- and macrovascular complications of diabetes." (PMID 25880202, 2015). "Notably, STZ-induced diabetes typically associates with a more scattered and dense appearance of insulin-positive islets." (PMID 26793108, 2015). "Diabetes mellitus is a metabolic disorder featured by hyperglycemia and alterations in carbohydrate, fat and protein metabolism associated with absolute or relative deficiency of insulin secretion and/or insulin action." (PMID 27047124, 2015). "Since insulin resistance contributes greatly to the metabolic syndrome and is the major cause of type 2 diabetes mellitus, treatment with insulin sensitizers may ameliorate the pathophysiological abnormalities of the metabolic syndrome." (PMID 26389944, 2015).
diabetes (continued). "Associations between dietary intake and adiponectin where observed, suggesting that dietary modifications may be a potential tool for improved insulin sensitivity and decreased risk for diabetes among Mexican Americans." (PMID 26703682, 2015). "The other reported diagnostic criteria for T1D were the need for insulin therapy (reported in 70 of 71 studies), clinical symptoms of diabetes (reported in 56 of 71 studies), low or normal body weight (14 of 71 studies), and ketosis or ketonuria (26 of 71 studies)." (PMID 25849566, 2015). "The mTOR signaling may be vital for proper insulin signaling in patients with diabetes since the loss of mTOR leads to hypoinsulinemia, glucose intolerance, insulin insensitivity to glucose secretion, and a decrease in β-cell size." (PMID 26083118, 2015). "This may also be associated with future diabetes incidence through greater postprandial glucose and insulin responses." (PMID 25787236, 2015). "This is true in the context of insulin-resistant and -deficient diabetes." (PMID 25870537, 2015). "Whether diabetes increases cancer risk through hyperinsulinemia alone or due to its combined effect on insulin and IGF-1 is still unclear." (PMID 25996963, 2015). "Metabolic syndrome is linked to insulin resistance, which may lead to diabetes when the body is unable to make enough insulin to keep the blood glucose within the normal range." (PMID 25852643, 2015). "Thus, conditions that impair β cell insulin production or cause the loss of these cells—as occurs with some forms of diabetes mellitus—can lead to metabolic derangement and even death." (PMID 26469794, 2015). "Since similar events occur the capillary beds of nerves, another insulin-insensitive tissue, topiramate may also help treat peripheral neuropathy caused by diabetes." (PMID 26120599, 2015). "The consensus is that the most important therapeutic endpoints of metformin are reduction in blood glucose level, and action as an insulin sensitizer, which is beneficial to patients with diabetes and/or potentially reduces the risk of most cancers including breast cancer." (PMID 25866793, 2015). "High insulin/IGF is a biologic link between diabetes and cancers, but the underlying molecular mechanism remains unclear." (PMID 26268733, 2015). "The Brazilian Longitudinal Study of Adult Health (ELSA-Brasil), a prospective cohort investigation of 15,105 Brazilian Adults from various regions of the country, provides a unique opportunity to study the association of coffee intake with diabetes and measures of glucose and insulin homeostasis." (PMID 25978631, 2015). "AGEs may directly contribute to induction or aggravation of diabetes causing progressive insulin secretory defects and pancreatic beta cell deaths and by enhancing insulin resistance via decreased biological activity of glycated insulin." (PMID 26000307, 2015). "Landmark studies in adult-onset type 1 diabetes (T1D) populations indicate that improved glycaemic control through use of intensive insulin therapy is strongly associated with reduced risk for the development of diabetes-related complications and mortality in later years." (PMID 26563100, 2015). "We found that diabetes was dose-dependently associated with urinary cooper, zinc, arsenic, selenium, molybdenum and tungsten after we excluded the participants who were using insulin treatment (P< 0.05)." (PMID 25874871, 2015). "Diabetes mellitus is a group of metabolic disorders caused by an abnormal carbohydrate metabolism and mainly linked to abnormal blood glucose and insulin levels or an ineffective response of cells to insulin." (PMID 26198246, 2015). "Our findings reveal novel mechanisms linking peripheral insulin sensitivity with cytoskeletal remodeling in neurons, which may help to explain the association of diabetes with neurological disorders such as Alzheimer disease." (PMID 26499801, 2015).
diabetes (continued). "However, it is noted that, in one meta-analysis retrospective study, data extracted from the Hong Kong Diabetes Registry reported that insulin replacement therapy reduced cancer risk." (PMID 25866793, 2015). "Hypoglycaemia presents a significant barrier to optimal diabetes management as fear of hypoglycaemic events may cause exaggerated avoidance behaviour and consequently sub-optimal insulin therapy and glycaemic control." (PMID 25421366, 2015). "It is well known that epinephrine excess can suppress insulin secretion and cause diabetes." (PMID 25774817, 2015). "Considering the association between vitamin D and insulin sensitivity and β-cell function, vitamin D supplement may be one promising way to improve insulin resistance and reduce risk of diabetes." (PMID 25741510, 2015). "Naturally occurring mutations in circuit genes affect insulin resistance and diabetes risk." (PMID 25774510, 2015). "Indeed, defects in insulin signaling contribute to diabetes-associated endothelial dysfunction and increased vascular permeability." (PMID 26696899, 2015). "Interestingly, in insulin-deficient rats and insulin-resistant mice, diabetes impairs hippocampus-dependent memory, impinging on both synaptic plasticity and adult neurogenesis, and the glucocorticoid system contributes to these adverse effects." (PMID 25977822, 2015). "We also found that arsenic remained associated with increased risk of diabetes after the subjects using insulin were excluded from the analyses, suggesting that association between urinary arsenic and diabetes risk in the population should not be regarded as of doubtful significance." (PMID 25874871, 2015). "Dysregulation of insulin-mediated metabolic pathways has emerged as as an underlying mechanism through which vitamin D deficiency, diabetes and obesity may be linked." (PMID 26095242, 2015). "Diabetes is a chronic disease characterized by high blood glucose level that results either from a deficiency of insulin produced by the body, or the body’s resistance to the effects of insulin." (PMID 26151207, 2015). "This decrease in insulin sensitivity or insulin resistance is one of a number of the metabolic changes associated with pregnancy, and 3–7% of pregnant women develop impaired glucose tolerance or diabetes." (PMID 25866757, 2015). "Diabetes severity may be a prime driver of breast cancer risk, and insulin is always used at a late stage of diabetes when pancreatic β cells are exhausted and most OAD fail to adequately control blood glucose." (PMID 26537234, 2015). "In studies from the UK, diabetes was mentioned in 42-43 % of death certificates of known diabetics, being associated with an increased duration of diabetes and insulin treatment, increasing age, female gender, low social class, and a cardiovascular underlying cause of death." (PMID 26309427, 2015). "We can distinguish two main types of diabetes: type 1 diabetes (T1D) in which the main cause is a deficiency of insulin production due to self-destruction of the pancreatic beta-cells and type 2 (T2D) in which the initial insulin resistance leads, with time, to an insulin deficiency." (PMID 26075282, 2015). "At the same time, insulin might be a marker of high-risk patients, not only because of more severe insulin resistance but also because of more prolonged diabetes mellitus." (PMID 26446829, 2015). "We found that antimony was associated with increased diabetes risk but the association attenuated to null after participants with insulin and other anti-hyperglycemia drug uses as well as subjects with a history of self-reported diabetes were excluded from the analysis." (PMID 25874871, 2015).
diabetes (continued). "The increased risk of diabetes with selenium exposure might be explained by selenium initiating an insulin signaling cascade accompanied by a burst of hydrogen peroxide." (PMID 25874871, 2015). "In insulin resistance, the IRS2 in kidney cortex is exceptionally preserved and may mediate the stimulatory effect of insulin on NBCe1 to cause hypertension in diabetes via sodium retention." (PMID 26491696, 2015). "We evaluated cross-sectional associations between coffee intake, newly diagnosed diabetes, fasting plasma glucose, two-hour plasma glucose during a 75g oral-glucose tolerance test, glycated hemoglobin, and measures of insulin resistance and beta-cell secretion." (PMID 25978631, 2015). "Finally, our findings of associations between adiponectin and dietary components suggest a need for future research to explore the effects of dietary components on adiponectin, insulin sensitivity, and diabetes risk in Mexican Americans." (PMID 26703682, 2015). "The United Kingdom Prospective Diabetes Study of 3867 patients with type 2 diabetes found that treatment with sulfonylureas or insulin vs. diet-based treatment significantly reduced the risk of myocardial infarction by 16%, but the effects on stroke, limb amputation or death were not significant." (PMID 26121301, 2015). "Moreover, weight gain is the most common side effect of many oral anti-diabetic agents and insulin, and increased weight has been shown to worsen glycemic control and increase the risk of diabetes progression." (PMID 25995968, 2015). "Additionally, new onset diabetes secondary to ADT can provide a mechanism for disease modification and castration resistance, since new onset diabetes is associated with hyperinsulinemia and insulin directly induces de novo steroidogenesis in PC cells." (PMID 26125012, 2015). "As hypothesized, our findings demonstrated that ERG dramatically recovered the levels of blood glucose and insulin, as well as other biochemical indicators linked to diabetes symptoms in serum and urine." (PMID 26664454, 2015). "It is known that type 1 diabetes mellitus results from insulin deficiency, usually secondary to autoimmune β-cell destruction; and type 2 diabetes mellitus requires defects in both β-cell function and insulin sensitivity." (PMID 25658748, 2015). "The association between diabetes and increasing age is related to the increase in glycated hemoglobin levels and the changes in insulin sensitivity which is measured by the Quantitative Insulin Sensitivity Check Index (QUICKI)." (PMID 26714019, 2015). "This may be advantageous since most therapies for diabetes such as insulin, insulin secretagogues, and thiazolidinediones are associated with an increase in food intake and weight gain." (PMID 25785281, 2015). "If this intrauterine programming results in a reduced β-cell mass, it could predispose to diabetes later in life when the insulin requirements increase as a consequence of obesity resulting in insulin resistance." (PMID 25774817, 2015). "In this study, an increased risk of fracture of 1.87 times was observed among persons treated with insulin and an increased risk of 1.63 times among persons with diagnosed diabetes with HbA1C ≥8 % (64 mmol/l) as compared to those individuals with HbA1C below 8 % [25••]." (PMID 25648962, 2015). "Sulfonylurea (SU), glitazones, incretin-based treatments, and insulin are potential subsequent treatment steps according to the recent consensus statement of the European Association for the Study of Diabetes and the American Diabetes Association." (PMID 25645672, 2015). "The link between African-Americans’ disproportionate rates of diabetes, obesity and vitamin D deficiency may be marked by C-peptide as an indicator of insulin secretion." (PMID 26095242, 2015). "However, our findings support the utility of adiponectin over adiposity measures as an indicator of insulin sensitivity and diabetes risk among Mexican Americans." (PMID 26703682, 2015).